MICA (MHC class I polypeptide-related sequence A)
Diseases named in the same sentence as MICA in open-access papers (continued):
Sharing a sentence is not in itself a finding about the gene and the disease.
hepatocellular carcinoma (70 papers, 2011 to 2026). A malignant tumor that arises from hepatocytes. "Silencing miR25-93-106b cluster significantly increased MICA expression and decreased the susceptibility of hepatocellular carcinoma cells to NKs." (PMID 32222150, 2020). "Another genome-wide association study identified a susceptibility locus in the 5′ flanking region of MICA for HCV-induced hepatocellular carcinoma." (PMID 30467624, 2019). "Our previous genome-wide association study identified the anti-tumor ligand MHC class I polypeptide-related sequence A (MICA) as a susceptibility gene for hepatitis C virus-induced hepatocellular carcinoma (HCC)." (PMID 29721164, 2018). "Genetic variants of MHC class I polypeptide-related chain A (MICA) at rs2596542 have been associated with hepatocellular carcinoma." (PMID 28427234, 2017). "Another MICA variant, rs23596542, was identified in hepatitis C virus induced hepatocellular carcinomas (HCC) from a Japanese population." (PMID 25972872, 2015). "We also provided evidence that low expression levels of MICA/B in human hepatoma tissues were significantly associated with a poorer outcome in patients with HCC." (PMID 25228093, 2014). "Since miRNA93 regulates the expression levels of the MICA protein, which is involved in the susceptibility to hepatocellular carcinoma in chronic hepatitis patients, we focused on this miRNA in further analyses." (PMID 25026299, 2014). "Moreover, the expression of MICA in tumor cells is closely associated with immune cells in hepatocellular carcinoma (HCC)." (PMID 40723248, 2025). "In line with our data, the MICA rs2596538 G allele variant was also identified as protective factor for hepatocellular carcinoma (HCC) in HCV-infected patients." (PMID 29867932, 2018). "Furthermore, UPR could downregulate MICA/B expression on hepatoma cells, and thereby rendered them less susceptible to NK cytolysis." (PMID 25228093, 2014). "Of note, HepG2-hNTCP cells express the NK cell modulating molecules CD155 and MICA/B, and as a hepatocellular carcinoma cell line, induce activation of NK cells also in the absence of HDV-infection." (PMID 38143742, 2023). "Accumulation of membrane-bound MICA (mMICA) enhances NK cell cytotoxicity against hepatoma cells, and mMICA cleavage releases soluble MICA (sMICA), which acts as an immunological decoy in the serum to prevent antitumor activity." (PMID 36572816, 2023). "In hepatocellular carcinoma, the miR-25-93-106b cluster significantly affected MICA expression, while its inhibition enhanced MICA expression." (PMID 36189271, 2022). "Knockdown of ADAM17 prohibits MICA shedding and boosts MICA expression on the surface of hepatocellular carcinoma cells." (PMID 36466812, 2022). "We previously identified a single-nucleotide polymorphism in the 5′-flanking region of the MICA gene on 6p21.33 (rs2596452) that leads to the development of hepatocellular carcinoma (HCC) in patients with chronic hepatitis by regulating MICA/B expression." (PMID 32968163, 2020). "The chemotherapeutics sorafenib and regorafenib inhibit shedding of MHC class I-related chain A (MICA) from hepatocellular carcinoma (HCC) cells by suppressing a disintegrin and metalloprotease 9 (ADAM9)." (PMID 32245188, 2020). "In a first set of experiments, the MICA/B-expressing Huh 7.5 hepatocellular carcinoma cell line was used as target." (PMID 33266137, 2020). "Recently, two GWAS variants, MICA rs2596542 and DEPDC5 rs1012068 were identified as being associated with the development of HCV-induced hepatocellular carcinoma (HCC) in Japanese patients." (PMID 30723271, 2019). "It is reported that hepatitis B virus (HBV) suppresses the expression of MICA/B on the surface of hepatoma cells and that the HBV core protein downregulates the expression of FAS." (PMID 30925759, 2019).
hepatocellular carcinoma (continued). "Consistent with the decreased expression of the A allele of the SNP rs2596538 and a relevant role of MICA for virus control, this allele constitutes a risk factor for hepatitis C virus (HCV) -related hepatocellular carcinoma." (PMID 29867932, 2018). "After blocking MICA/B on hepatoma cells with an anti-MICA/B antibody or blocking of NKG2D on NKL cells with an anti-NKG2D antibody, the cytolytic activity of NKL cells decreased significantly." (PMID 27528231, 2016). "The MICA/HCP5 region has been linked to NPC susceptibility and HCV-associated hepatocellular carcinoma." (PMID 26730743, 2016). "HBsAg has been reported to inhibit MICA expression via induction of cellular miRNAs in hepatocellular carcinoma cells." (PMID 27528231, 2016). "Due to the critical role of NKG2D and its ligands in the defense against virus infection and tumorigenesis, clarifying how HBV suppresses MICA expression on hepatoma cells and contributes to escape from NK cell lysis is an important line of investigation." (PMID 27528231, 2016). "This is in line with the report by Morisaki and coworkers, who reported that Gemcitabine enhances the expression of MICA/B in the hepatocellular carcinoma line HepG2, but the molecular mechanisms of the Gemcitabine-induced MICA/B expression was not analyzed." (PMID 26439264, 2015). "MICA/B are major ligands for NK cell activating receptor NKG2D and previous studies showed that the serum level of soluble MICA (sMICA) is an independent prognostic factor for advanced human hepatocellular carcinoma." (PMID 25228093, 2014). "To further clarify the function of MICA/B in hepatoma cells during UPR, we assessed if reduced expression level of MICA/B on hepatoma cells undergoing UPR had any effects on NK cells cytotoxicity against hepatoma cells." (PMID 25228093, 2014). "Further experiments confirmed this conjecture: the reduction of MICA/B expression in hepatoma cells during the UPR was at least partly due to proteasomal degradation." (PMID 25228093, 2014). "It was found that the expression level of MICA/B was significantly higher in the hepatoma cells at early stages (stages T1 and T2) compared to that of the hepatoma cells at advanced tumor stages (stages T3 and T4)." (PMID 25228093, 2014). "In this study, we systematically investigated the protein expression of MICA/B in 5 normal liver tissues and 96 hepatocellular carcinoma tissues." (PMID 25228093, 2014). "We recently reported that a single nucleotide polymorphism (SNP) rs2596542 located in the MICA promoter region was significantly associated with the risk for hepatitis C virus (HCV)-induced hepatocellular carcinoma (HCC) and also with serum levels of soluble MICA (sMICA)." (PMID 23024757, 2012). "MICA is broadly expressed in a variety of malignancies, including melanoma, breast, colon and hepatocellular cancers." (PMID 21605422, 2011). "In addition to regulating the expression of MICA in hepatoma cells, metalloproteinases can also regulate the activity of immune cells in the tumor microenvironment and thereby affect the progression of liver cancer." (PMID 40563539, 2025). "In hepatocellular carcinoma, inhibition of checkpoint kinase 1 (CHK1) increases IRF1 expression to induce apoptosis and trigger antitumor immunity through major histocompatibility complex (MHC) class I-associated chain A (MICA)." (PMID 38789431, 2024). "Soluble MICA was found significantly elevated in the sera of patients with leukemia, colorectal cancer, prostate cancer, lung cancer, ovarian cancer, prostate cancer, breast cancer, pancreatic cancer, oral squamous cell cancer and hepatocellular cancer." (PMID 34077462, 2021). "Our previous study indicated that peptides could regulate he p38/MAPK pathway to increase MICA/B expression in hepatocellular carcinoma cells, whereas the CTL epitope upregulating MICA/B expression on DCs to activate NK cells has not been reported." (PMID 33910591, 2021).
hepatocellular carcinoma (continued). "In an in vitro drug screen using a Federal Drug Administration-approved drug library, lomofungin, an antifungal drug, was found to strongly decrease ADAM17 activity in hepatocellular carcinoma cells and resulted in enhanced membrane bound MICA expression and inhibited soluble MICA production." (PMID 30805309, 2019). "Recently, the MICA rs2596542 and DEPDC5 rs1012068 variants in Japanese individuals as well as the HCP5 rs2244546 and PNPLA3 rs738409 variants in European individuals have been found associated with hepatocellular carcinoma (HCC)." (PMID 28928439, 2017). "Vorinostat can regulate miR-17-92 cluster and MCM7 to upregulate MICA expression in hepatoma." (PMID 28572863, 2017). "We first ascertained the pharmacological upmodulation of MICA expression in hepatoma cells." (PMID 27910927, 2016). "In the present study, we demonstrated that the HBx and HBc could suppress the expression of MICA in hepatoma cells, thus leading to decreased susceptibility of HBV+ hepatoma cells to NK lysis." (PMID 27528231, 2016). "Further epigenetic changes may be required for MICA/B overexpression since MICA/B promoter methylation regulates MICA/B gene expression in hepatomas." (PMID 21605422, 2011). "MICA/B shedding from the membrane of cancer cells can inhibit natural killer (NK) cells from attacking hepatocellular carcinoma (HCC)." (PMID 41792898, 2026). "ADAM9 knockdown experiments have revealed that ADAM9 is involved in MICA ectodomain shedding of human hepatocellular carcinoma (HCC) cells before." (PMID 35740916, 2022). "MiRNAs that target MICA include miR-93, miR-106b, miR-106a, miR-373, miR-20a in hepatocellular carcinoma (HCC), miR-519a-3p, miR-20a in breast cancer, and miR-125b in multiple myeloma." (PMID 34122412, 2021). "In this study, we observed that the average serum soluble MICA (sMICA) concentration of 174 hepatocellular carcinoma (HCC) patients was significantly higher than that in 80 healthy subjects (602.17 ± 338.15 vs. 72.26 ± 87.88 pg/ml, t = 3.107, P=0.002)." (PMID 32010486, 2020). "However, whether GATA-2 and GATA-3 are involved in MICA/B expression in hepatoma cells is still unknown." (PMID 27528231, 2016). "HDV infection did not significantly change the cell surface expression of the NK cell ligands MICA/B, NKp30/44 ligands, CD54, CD112, OX40L, HVEM, B7H6 and PD-L1 or the expression of HLA molecules on infected hepatoma cells." (PMID 38143742, 2023). "A recent study shows that the histone deacetylase inhibitors (HDACi) SAHA epigenetically upregulates MICA expression through regulating the expression of miR-17-92 cluster and MCM7 in hepatoma." (PMID 32748943, 2020). "Recently, the pharmacological agent disulfiram (DSF) was effective to suppress MICA shedding, impairing ADAM10 activity in hepatocellular carcinoma." (PMID 32269567, 2020). "In a model of hepatocellular carcinoma, treatment with the histone deacetylase inhibitor, valproic acid (VPA), resulted in increased MICA and MICB cell-surface levels and simultaneous enhancement of their soluble forms in the conditioned media." (PMID 32269567, 2020). "Expression of MICA and MICB on transformed hepatocytes was also observed on hepatoma cell lines, HCCs, and carcinoma cell lines." (PMID 30150983, 2018). "MICA was attached to rG7S, a single-chain antibody fragment (scFv) targeting the tumor-associated antigen CD24 to form a fusion protein rG7S-MICA to treat hepatocellular carcinoma (HCC)." (PMID 28036020, 2016). "Furthermore, both cohorts demonstrated a significant relationship between the high expression of TMEM201 and the increased expression of MICA, which was confirmed in the si-TMEM201 hepatoma cell lines." (PMID 37373430, 2023). "NKG2D ligands, including MICA, MICB, and ULBPs, can be widely expressed in hepatoma cells." (PMID 32075046, 2020).
hepatocellular carcinoma (continued). "Furthermore, NB and hepatoma cells treated with VPA have shown increased sensitivity to NK cell killing through transcription of MHC class I-related chain A and B (MICA and MICB)." (PMID 28572863, 2017). "Indeed, decreased expression of the NKG2D ligands, MICA/B, on HBV-infected human hepatoma cells has been shown to depress NK cells lysis." (PMID 27528231, 2016). "We also studied the value of MICA/B for prognosis in HCC patients and showed that the expression levels of MICA/B on hepatoma cells were significantly down-regulated during UPR, which consequently led to more resistance of hepatoma cells to NK cell cytotoxicity." (PMID 25228093, 2014). "Although the treatment of different hepatoma cell lines with the ER stress inducer tunicamycin reduced the protein levels of MICA/B on hepatoma cells, this is not accompanied by a reduction of MICA/B mRNA during the UPR." (PMID 25228093, 2014). "After patients were treated with chemotherapy, the DNA of hepatoma cells was damaged, and interferon regulatory factor 1 (IRF1) was activated, stimulating M2 macrophages to secrete a large amount of MMP9 in the form of exosomes to hydrolyze MICA on the surface of hepatoma cells." (PMID 40563539, 2025). "The results showed that the level of MICA/B secretion was significantly enhanced in senescent cells, with that in IMR-32 being significantly higher than several other cell lines, which is consistent with previous results in multiple myeloma and hepatocellular carcinoma." (PMID 35309907, 2022). "Furthermore, ligands (such as ULBPs and MICA) of NK cells activating receptor NKG2D, which are essential for NK cell lytic activity, are downregulated in gliomas and hepatocellular carcinoma (HCC) cells via DNA methylation and histone methylation, respectively." (PMID 33535484, 2021). "In hepatoma cells, athough it seems that HBx-induced GATA3/2 activation and Ap-1 or SP-1 activation might results in opposite effect on MICA expression, we indeed observed that HBx suppresses MICA expression in our experiments." (PMID 27528231, 2016). "In detail, Armeanu and colleagues demonstrated an enhancement of cell-surface expression of MICA/B in HepG2 and Hep3B hepatoma cells with no alterations of ULBP1-3 levels upon stimulation with the HDAC inhibitor valproic acid (VPA), which led to an enhanced NK cell-mediated killing." (PMID 27142426, 2016). "However, the correlation between hepatocellular carcinoma progression and membrane-bound MICA/B expression has not been well explored." (PMID 25228093, 2014). "However, the correlation between cellular MICA/B expression pattern and human hepatocellular carcinoma progression has not been well explored." (PMID 25228093, 2014). "BCR/ABL, for example, regulates MICA, but not ULBP1-2 in K562 cells, while histone deacetylase inhibitor induces MICA, but not ULBP1-3 in hepatoma cells." (PMID 25510288, 2014). "Treatment of a hepatocellular carcinoma cell (HCC) line with sorafenib did not affect HLA class I expression but increased membrane-bound MICA and decreased soluble MICA resulting in enhanced NK cell-mediated cytotoxicity." (PMID 23316191, 2012).
breast cancer (49 papers, 2014 to 2025). A primary or metastatic malignant neoplasm involving the breast. "MICA-129Met homozygosity confers susceptibility to inflammatory bowel disease, while MICA-129Val homozygosity leads to faster progression of multiple myeloma (MM) and also plays a role in susceptibility for breast cancer development." (PMID 34394116, 2021). "A study of the Vγ9Vδ2 γδTc subset in the context of breast cancer suggested that surface levels of MICA/B on breast cancer target cell lines were associated with γδTc cytotoxicity against these lines; however, direct blocking assays were not carried out." (PMID 29963058, 2018). "Functional analyses in this study demonstrated that resveratrol increased the susceptibility of breast cancer cells to lysis by NK cells in vitro and in vivo by inducing MICA and MICB expression." (PMID 29029468, 2017). "Our findings in breast cancer cells and animal models prompted us to investigate the clinical association of miR-17 with MICA/B and its prognostic impact on breast cancer patients." (PMID 29029468, 2017). "In breast cancer, MICA/B ligands and ULBP2 are associated with a longer relapse-free period." (PMID 40013140, 2025). "In addition, there was a decrease in MICA expression in older people who are at high risk of developing breast cancer." (PMID 32784928, 2020). "In breast cancer, elevated MICA expression was found more commonly in high-grade poor prognosis tumours." (PMID 37626965, 2023). "Illustrating this, the co-expression of the HER2/HER3 heterodimer resulted in the enhanced expression of MICA/B in breast cancer cell lines." (PMID 37626965, 2023). "To evaluate the expression of NKG2DL in primary breast cancer material (n = 200), we used the TCGA database analysis and observed predominant expression of MICA, MICB and ULBP2." (PMID 37685962, 2023). "In breast cancer stem cells, high levels of miR-20 induced a downregulation of MICA and MICB, which consequently decreased the capability of NK cells to mediate cell killing and promote the metastatic ability of cancer cells." (PMID 36189271, 2022). "We also observed that breast cancer cells expressed a high level of MICA/MICB, which was a kind of ligands of NKG2D." (PMID 35894707, 2022). "MICA is overexpressed in breast cancer when compared to normal tissue and is considered an indicator of poor prognosis." (PMID 36338974, 2022). "Fusion protein MICA-G129R was confirmed not only able to bind to PRLR-positive breast cancer cells and NK cells, but also enhance cytotoxicity of NK cells on PRLR-positive cells." (PMID 34077462, 2021). "In breast cancer, miR-20a was found to inhibit the expression of MICA/B and ULBP2 by directly targeting MICA/B and downregulating ULBP2 through inhibition of MAPK/ERK, which ultimately resulted in a decrease in the cytotoxicity of NK cells." (PMID 34084160, 2021). "In one of the studies, γδ T cells, in the context of breast cancer, suggested that surface levels of MICA/B on breast cancer cells enhanced targeting and cytotoxicity by γδ T cells against these cell lines." (PMID 34322393, 2021). "When binding to PRLR, the fusion protein labels the breast cancer cells with MICA, which attracts and activates NK cells to kill the breast cancer cells." (PMID 34077462, 2021). "Due to the wide expression of PRLR in almost all types of breast cancers, fusion protein MICA-G129R can be used for many types of breast cancers regardless the common classification with ER, PR, HER2 or triple negative breast cancers." (PMID 34077462, 2021). "The in vivo interaction of human NK cells and MICA-G129R can be investigated in immunodeficiency mice xenografted with human PRLR-positive breast cancer cells." (PMID 34077462, 2021). "Specifically, breast cancer patients with high expression of MICA and ULBP2 show better outcome with relapse free periods, that is further enhanced when both ligands are highly expressed in this type of tumor." (PMID 32784928, 2020).